GBA1 (glucosylceramidase beta 1)
Diseases named in the same sentence as GBA1 in open-access papers (continued):
Sharing a sentence is not in itself a finding about the gene and the disease.
cancer (17 papers, 2015 to 2026). A tumor composed of atypical neoplastic, often pleomorphic cells that invade other tissues. "Several mechanisms have been proposed to account for the cancer susceptibility associated with GBA1 mutations." (PMID 41300754, 2025). "Patients harboring GBA1 mutation had a rather low percentage of a positive history of cancer (6 patients out of a total of 107, prevalence 5.61%)." (PMID 41300754, 2025). "Thirty-seven significantly associated cancer–gene pairs and four genes (GBA1, SGSH, HEXA, and CLN3) with a Pan-Cancer association were identified (Pan-Cancer is a cohort of 2567 patients with cancer)." (PMID 39404425, 2024). "Up-regulation of GCS is implicated in cancer progression and multi-drug resistance, but the role of glucosylceramide breakdown (including GBA1 and GBA2) in cancer is unclear." (PMID 35330102, 2022). "Taken together, these data suggest that the presence of a GBA1 germline mutation or a somatic amplification may influence cancer pathogenesis and/or response to therapies through context-dependent mechanisms that are still to be characterized." (PMID 41857000, 2026). "Furthermore, GBA1 expression is elevated in different cancer tissues, compared with healthy counterparts and associated with outcome in some cases." (PMID 41857000, 2026). "Supporting this, Taddei and colleagues reported that in a cohort of 367 Ashkenazi Jewish GD patients (54% homozygous for the N370S GBA1 mutation), long-term follow-up revealed heightened risks of both cancer in general and hematologic malignancies in particular." (PMID 41300754, 2025). "At this point, it is unclear whether GBA1 is itself a cancer gene or if carriers of GBA1 mutation have an elevated risk of cancer." (PMID 30906609, 2019). "In this perspective, we narratively review the main evidence supporting a role for GBA1 in influencing tumorigenesis and we present our analyses on GBA1 amplification and expression throughout different cancer types." (PMID 41857000, 2026). "The distinctive contribution of this study lies in its examination of genetic forms of PD—including carriers of LRRK2, GBA1, SNCA, PRKN, and PINK1 mutations—in relation to cancer risk." (PMID 41300754, 2025). "The percentage of livers with cancer formation was higher in the mice injected with GBA1-silenced Huh7 cells than in the mice injected with control Huh7 cells." (PMID 35637196, 2022). "GBA1-regulated ceramide in cancer cell lines is suggested to down-regulate activation of p38δ by activating ceramide-activated protein phosphatases." (PMID 26312487, 2015). "Notably, a large fraction of patients affected by different cancer types carry an amplification of the long arm of chromosome 1, that includes the GBA1 gene." (PMID 41857000, 2026). "siRNA for GBA1 gene was shown to induce resistance to Taxol in three different cancer cell lines." (PMID 34637456, 2021). "No cases of cancer were reported in the dual LRRK2/GBA1 mutation carriers." (PMID 41300754, 2025). "Thus, while GBA1 carriers differed statistically from those with iPD in terms of cancer occurrence, no directional risk association could be established." (PMID 41300754, 2025). "The analysis of GBA1 carriers also yielded statistical significance (χ2 = 9.531, p = 0.0020); however, the estimated effect size was close to zero (95% CI: −6.49% to +5.91%), suggesting that the result reflects heterogeneity rather than a consistent increase or decrease in cancer risk." (PMID 41300754, 2025). "Increased expression of glucosylceramide synthase (GCS) contributes to drug resistance and the progression of various cancers; the expression profiles of GCS (UGCG) and the genes for glucocerebrosidases 1, 2, and 3 (GBA1, GBA2, and GBA3) were therefore studied in CCA." (PMID 35330102, 2022).
neurological disease (16 papers, 2012 to 2026). "Collectively, our data suggests that fusion proteins comprising GCase and TfR binders represent a promising therapeutic approach for GD type 2 and 3 and potentially other GBA1-associated neurological diseases." (PMID 37045813, 2023). "Overall, for affected individuals, most (>85%) respondents were comfortable returning clinically relevant pathogenic variants in PD genes and >70% were comfortable returning the results on GBA1 variants or pathogenic variants in other neurologic disorder-related genes." (PMID 39807215, 2024). "Brain tissue was used because of GBA1’s importance in neurological disease and previous evidence suggesting that transcriptome annotation is most incomplete in human brain." (PMID 38924406, 2024). "To address this gap in knowledge, we examined quantitative protein pathology, glucocerebrosidase activity and lipid substrates in parallel from 4 regions of 91 brains with no neurological disease, idiopathic, GBA1-linked, or LRRK2-linked PD and DLB." (PMID 37169750, 2023). "The disease is a consequence of pathogenic variants in the glucocerebrosidase gene (GBA1) (MIM*606403) and can be classified into three clinical subtypes based on the age of onset, clinical signs, rate of progression, or absence of neurologic disease." (PMID 39201273, 2024).
tumor (11 papers, 2015 to 2025). "In contrast, the tumour volume in mice injected with GBA1-silent Huh7 cells was higher than that in the control group." (PMID 35637196, 2022). "According to the GEO database, GCS was overexpressed in CCA tumor tissues and showed higher expression than the two glucosylceramide-degrading enzymes, GBA1 and GBA2." (PMID 35330102, 2022). "This enhanced Gba1 expression catalyzes the degradation of glucosylceramides to ceramides responsible for tumor regression, and lowers the glucosylceramide levels critical for drug resistance." (PMID 33568634, 2021). "Recently, our group has shown that a combination chemotherapy induces the AS in glucocerebrosidase β (Gba1), and increases Gba1 expression in murine tumor tissues." (PMID 33568634, 2021). "GCS expression was higher in CCA tumor tissues than that of GBA1, GBA2, and GBA3." (PMID 35330102, 2022). "Additionally, the expression level of GCS was higher in the CCA tumor tissues than the other glucocerebrosidase (GBA1, GBA2, and GBA3)." (PMID 35330102, 2022). "Both the GCS and the GBA1 expression levels were significantly up-regulated in CCA tumor tissues, whereas the GBA2 and GBA3 were down-regulated compared with matched paired non-tumor CCA tissues." (PMID 35330102, 2022).
genetic disease (7 papers, 2015 to 2025). "GD is a rare genetic disease where mutations of the GBA1 gene link to enzyme deficiency and substrates accumulation of Gb-1 and lyso-Gb-1 in various tissues, including the bone marrow." (PMID 40671914, 2025).
infection (7 papers, 2012 to 2025). The state of being infected such as from the introduction of a foreign agent such as serum, vaccine, antigenic substance or organism. "The inability for disease caused by infection with the gba1 strain to progress beyond chlorosis however, may implicate necrotrophic effector production in S. nodorum as positively regulated by G-protein signalling through the Gβ subunit Gba1." (PMID 22759704, 2012). "Epigenetic modification (GBA1 gene demethylation): In gastric carcinogenesis, infection triggers demethylation of the glucocerebrosidase (GBA1) gene promoter, leading to its upregulation." (PMID 41158522, 2025). "Whereas most macrophages in gba1 mutant brains had the Gaucher cell phenotype, these were a distinct minority among those that were recruited to infection." (PMID 36745788, 2023). "Significantly more gba1 mutant zebrafish had cleared infection, confirming that their macrophages were more microbicidal to mycobacteria." (PMID 36745788, 2023). "Fewer bacteria were present in the HBV at 3 d after infection (dpi) in the homozygous gba1 mutant fish than in their wild-type siblings." (PMID 36745788, 2023). "S. nodorum gna1, gba1 and gga1 were all unable to sporulate during infection of the wheat leaf, however although this defect may slow disease amplification, sporulation is clearly not a prerequisite for leaf necrosis." (PMID 22759704, 2012). "In addition, the residual GBA1 and GBA2 activities associated with heat killed bacteria were measured by enzymatic assays on the amounts of heat killed PAO1 from 20 to 30-fold higher compared to those used for the cell infection." (PMID 25141135, 2014). "A significant increase in total β-glucosidase, GBA1 and GBA2 activities were observed in response to infection." (PMID 25141135, 2014).
movement disorder (7 papers, 2019 to 2026). Neurological conditions resulting in abnormal voluntary or involuntary movement, which may impact the speed, fluency, quality and ease of movement. "We investigated the basis and clinical correlates of a negative cerebrospinal fluid (CSF) alpha-synuclein (α-syn) seed amplification assay result in patients with a clinical diagnosis of sporadic or GBA1-associated PD formulated by movement disorder specialists." (PMID 41980956, 2026). "The trial will enrol 330 PD patients with confirmed GBA1 status and the primary outcome will be the combined score of parts I, II, and III of the Movement Disorders Society-Unified Parkinson's Disease Rating Scale (MDS-UPDRS)." (PMID 41708985, 2026).
cardiovascular disease (3 papers, 2015 to 2025). "Two patients in our cohort, homozygous for the GBA1 p.Asn409Ser mutation, had cardiovascular disease." (PMID 41282474, 2025).
hematologic malignancies (2 papers, 2025). "Heterozygous P/LP variants in genes associated with other hematopoietic diseases or developmental disorders with autosomal recessive inheritance were identified in ADAMTS13, GBA1 (n=3), and VPS13B." (PMID 40766138, 2025).
psychiatric diseases (2 papers, 2024 to 2025). "Our findings suggest that SNCA, GBA1, and UGCG analysis could be instrumental in the search for biomarkers of MDD and in understanding the overlapping pathological mechanisms underlying neuro-psychiatric diseases." (PMID 38542193, 2024).
skeletal disease (2 papers, 2023 to 2024). "Our results underscore the critical roles of ER stress and inflammasome activation in the differentiation of GBA1-deficient monocyte osteoclasts, shedding light on the mechanisms that underpin bone disorders associated with GBA1 mutations." (PMID 38575988, 2024).
GBA1 also shares sentences with these, for which no sentence is quoted: metabolic disorder (12 papers); sphingolipidosis (8); Krabbe disease (7); Ataxia (5); anemia (4); gastric cancer (4); orthostatic hypotension (3); tauopathies (3); Atrophy (2); autosomal recessive disease (2); bacterial infections (2); cerebellar ataxia (2); chronic neuronopathic Gaucher disease (2); Constipation (2); frontotemporal dementia (2); GM1 gangliosidosis (2); lymphoma (2); lysosomal lipid storage disorder (2); Niemann-Pick disease type A (2); osteonecrosis (2); Osteopenia (2); parkinsonian disorder (2); prion disease (2); Stroke (2); Tay-Sachs disease (2); tuberculosis (2); Akinesia (1); alcohol use disorder (1); Apathy (1); apraxia (1).
A further 71 diseases each share a sentence with GBA1 in 1 paper.